KDM5B (lysine demethylase 5B)
Diseases named in the same sentence as KDM5B in open-access papers (continued):
Sharing a sentence is not in itself a finding about the gene and the disease.
breast carcinoma (continued). "Consistent with its anti-oncogenic function, KDM5B was downregulated in ER− breast cancer cells and overexpression of KDM5B suppressed genes involved in cell proliferation, immune response, as well as angiogenesis and cell migration." (PMID 27974677, 2017). "Inhibiting KDM5B in breast cancer cells has been shown to reduce proliferation-reduced mammary tumor growth in vitro and in vivo." (PMID 28055972, 2017). "A subsequent study verified an increased expression of KDM5B in human primary breast cancer samples compared with normal tissue and human breast cancer-derived cell lines." (PMID 27974677, 2017). "KDM5B was initially identified as a gene that was up-regulated by the tyrosine kinase HER2 signaling in breast cancer and inhibited signaling from the c-erbB2 receptor." (PMID 27974677, 2017). "Increased expression of KDM5B in breast cancer was related with poor prognosis, suggesting that KDM5B had tumor promoting activities." (PMID 27974677, 2017). "KDM2A along with KDM5B, have the highest frequency of gene amplifications and over expressions in breast cancer with respect to JmjC enzymes." (PMID 28536364, 2017). "We demonstrated that KDM5B is a surrogate prognostic biomarker of breast cancer progression and represents a therapeutic target in metastatic breast cancer." (PMID 26917489, 2016). "In our validation cohort, KDM5B was strongly expressed in 49.2 % (n = 270) of the breast cancer samples." (PMID 26917489, 2016). "Increased expression of KDM5B correlating with disease progression and poor clinical outcome in breast cancer was reversed by hsa-miR-448." (PMID 26917489, 2016). "KDM5B has been recently shown to be over-expressed in luminal breast cancers, where high activity of this gene has also been correlated to poor outcomes in ER+ patients." (PMID 27341628, 2016). "KDM5B ablation attenuated tumor cell migration, invasion, clonogenicity, and mammosphere formation ability of breast cancer cells, (iv)." (PMID 26917489, 2016). "This is consistent with our earlier findings that suggested that KDM5B plays a critical role in the formation and maintenance of breast cancer stem cells (BCSCs)." (PMID 26917489, 2016). "To investigate the effect of KDM5B on the proliferation and malignant phenotype of breast carcinoma cells, we performed cell proliferation, mammosphere formation and colony formation assays." (PMID 26917489, 2016). "There was increased proliferation, mammosphere generation and colony formation in the KDM5B-positive vector breast cancer cells, while cells with attenuated KDM5B expression exhibited reduced proliferation, mammosphere formation and clonogenicity ability." (PMID 26917489, 2016). "Both univariate and multivariate analyses using the Cox proportional hazards model showed that KDM5B expression, lymph node metastasis, and tumor size were all significant predictors of breast cancer biochemical and clinical outcome." (PMID 26917489, 2016). "Our immunohistochemistry analysis of metastatic human breast cancer samples indicated a positive correlation between KDM5B expression, advanced tumor stage and poor clinical outcome of patients." (PMID 26917489, 2016). "human breast carcinoma samples exhibited the highest expression of KDM5B and MALAT1 in advanced stage (T3 and T4) cancer with associated poorer overall survival." (PMID 26917489, 2016). "To understand the biofunctional significance of KDM5B in human breast cancer, using bioinformatics approach, we accessed and probed the TCGA invasive lobular and ductal breast carcinoma dataset consisting of 593 samples via the Oncomine interface." (PMID 26917489, 2016). "KDM5B was first identified and characterized in 1999 when Lu found its overexpression in human breast-cancer cell lines and primary breast carcinomas." (PMID 26911146, 2016).
breast carcinoma (continued). "Our finding that H3K4me3 decreases in response to Tat-SID-mediated disruption of KDM5B is in agreement with recent studies in which KDM5B has been knocked down in embryonic stem cells or breast cancer cell lines, as well as in a mouse knockout model." (PMID 26460951, 2015). "KDM5B is involved in transcriptional repression and breast cancer cell proliferation; thus, mechanistic studies on KDM5B demethylation are necessary and useful to understand the development of breast cancer." (PMID 24952722, 2014). "Given the convergence of four breast-cancer-associated genes (EMSY, ETS-1, KDM5B, and miR-31) with overlapping biological roles, this pathway offers a number of avenues for therapeutic intervention." (PMID 24582497, 2014). "KDM5B has low expression levels in normal adult tissue, except in the testes, but it is found overexpressed in the bladder, prostate and breast cancer." (PMID 25145438, 2014). "KDM5B has been shown to be overexpressed in several cancers, such as breast, prostate, and lung cancer, and is required for mammary tumor formation in xenograft mouse models." (PMID 24582497, 2014). "Down-regulation of expression of KDM5B using shRNAi in the breast cancer cell line MCF-7 cells result in a dramatic decrease in E2 stimulated tumor growth in nude mice." (PMID 23579952, 2013). "Previous studies showed KDM5B overexpression in advanced breast carcinoma and breast cancer cell lines." (PMID 21886846, 2011). "Consistent with KDM5B overexpression in malignant breast tumors, a highly increase in KDM5B level was observed in cDNA samples from primary ductal breast adenocarcinomas." (PMID 21886846, 2011). "Overall, these findings establish a novel regulatory axis in cholesterol metabolism, uncover potential therapeutic vulnerabilities in ER+ breast cancer, and suggest that targeting the KDM5B could provide a strategy to curb tumor progression." (PMID 41654562, 2026). "Additionally, KDM5B overexpression and knockdown were performed to investigate the role of KDM5B in breast cancer cell proliferation and progression." (PMID 41654562, 2026). "Our findings highlight the repurposing potential of ABC to target KDM5B in breast cancer." (PMID 40764352, 2025). "KDM5B, a lysine-specific histone demethylase, is widely upregulated in breast cancer." (PMID 40764352, 2025). "KDM5B expression was elevated in breast cancer tissues compared to normal breast tissues." (PMID 40764352, 2025). "Therefore, KDM5B silencing in breast cancer reprograms lipid metabolism to stimulate the migration and proliferation of breast cancer cells via activation of AMPK." (PMID 38715072, 2024). "Knockdown of KDM5B inhibits the proliferation, migration, and invasion of breast cancer cells." (PMID 39039611, 2024). "We showed that KDM5B-NTT over-expression in breast cancer cell lines leads to a significant increase in H3K4 tri-methylation of bulk chromatin and transcriptional induction of several genes, including genes previously found directly regulated by the canonical PLU-1 isoform." (PMID 39000010, 2024). "KDM5B, ARSB, AKR1C3, HSD3B1, ESRRB are involved in steroid hormone metabolism and have been found to be associated with other hormone-dependent tumors, such as prostate and breast cancers." (PMID 36742386, 2023). "Therefore, this aspect adds a higher level of complexity, which in the future should be taken into account to fully appreciate the relevance of KDM5B-NTT in fine-tuning KDM5B-PLU-1 isoform activity in different breast cancer subtypes." (PMID 36697763, 2023). "Indeed, a significant fraction of KDM5B-NTT-modulated genes was previously shown to bind to KDM5B in MCF7 or other breast cancer cell lines." (PMID 36697763, 2023). "KDM5B promotes breast cancer cell proliferation and migration by reprogramming lipid metabolism." (PMID 37394582, 2023).
breast carcinoma (continued). "Previous work supports a role for KDM5B in cultured breast cancer cell proliferation, and its predicted inhibition in our dataset may represent a compensatory mechanism in response to sustained proliferative signaling by BPA alternative chemicals." (PMID 36534918, 2023). "Additionally, breast cancer patients demonstrated that KDM5B inhibition triggered an interferon response, resulting in resistance to DNA and RNA viral infections, thereby proposing a role for KDM5B as a COVID-19 prevention target." (PMID 36293144, 2022). "This evidence supports the notion that KDM5B is oncogenic in ER+ breast cancer." (PMID 35805040, 2022). "KDM5B also interacts with ER and enhances E2-dependent tumor growth in ER+ breast cancer cells." (PMID 35805040, 2022). "The expression of KDM5B is relatively lower in TNBC than in ER+ breast cancer." (PMID 35805040, 2022). "KDM5B was first identified as an upregulated gene in breast cancer." (PMID 35805040, 2022). "KDM5B is upregulated in breast cancer and is positively correlated with metastasis." (PMID 35846145, 2022). "Subsequent studies further delineated the functions of KDM5B in breast cancer." (PMID 35805040, 2022). "Indeed, H3 tail binding by PHD1 was required for the stimulation of breast cancer cell migration upon KDM5B overexpression, indicating a physiological relevance of this interaction." (PMID 35899196, 2022). "In breast cancer, KDM5B and E-cadherin present reverse patterns of expression." (PMID 34493070, 2021). "However, downregulation of KDM5B had the opposite effect on luminal epithelial breast cancer cell lines, MCF-7 and T47D, and resulted in downregulation of Nanog expression in these cells." (PMID 31776402, 2019). "However, the mechanisms by which KDM5B is regulated in breast cancer, in particular in response to post-translational signals is not well-defined." (PMID 31776402, 2019). "Indeed, KDM5B was initially identified as a gene markedly overexpressed in breast cancer even before the discovery of histone lysine demethylases." (PMID 31060229, 2019). "In breast cancer, increased KDM5B expression drives a luminal cell-specific expression program." (PMID 31776402, 2019). "KDM5B is up-regulated in breast cancer cells overexpressing the ERBB2/HER2 oncogene." (PMID 30080846, 2018). "KDM5B was identified as a gene up-regulated by HER2 in human breast cancers." (PMID 30080846, 2018). "In addition, COLT analysis of the genes essential for cancer cell survival and proliferation in 29 breast cancer lines identified KDM5B as a hit in 12 (41%) of these lines." (PMID 28055972, 2017). "In MCF7 cells and in a mouse breast cancer model, depletion of KDM5B inhibits cell growth." (PMID 28536364, 2017). "KDM5B was originally discovered as a gene that was upregulated by HER2 in breast cancer cells." (PMID 28055972, 2017). "In addition, down-regulation of KDM5B by shRNA decreased tumor formation potential both in a syngeneic mouse mammary tumor model and in xenografts models." (PMID 27974677, 2017). "Thus, we inferred that the difference in the malignant invasive potential of the breast cancer cells was due to their differential KDM5B expression." (PMID 26917489, 2016). "Using immunohistochemical staining, we confirmed the endogenous expression of KDM5B in breast cancer samples and correlative analysis showed that KDM5B expression level positively correlated with tumor histological grade (p < 0.001), with highest expression in grade IV." (PMID 26917489, 2016). "KDM5B expression is significantly up-regulated in bladder cancer, acute myelogenous leukemia, breast cancer, chronic myelogenous leukemia, cervical cancer and renal cell carcinoma compared with corresponding non-neoplastic tissues, indicating its involvement in many types of human cancer." (PMID 23579952, 2013). "JARID1B (PLU1 or KDM5B) was shown to be overexpressed in breast cancer celllines." (PMID 24172249, 2013).
breast carcinoma (continued). "However, it has been suggested that KDM5B may have different functions in luminal and basal breast cancer cell lines." (PMID 36697763, 2023). "Furthermore, we sorted the basal breast cancer patients from low to high according to their mRNAsi values and found that patients with high mRNAsi are usually accompanied by high expression of tumor stem-related genes such as KDM5B, BMI1, MYC, and EZH2." (PMID 34646403, 2021). "In addition, we assessed the expression levels of KDM5B in breast cancer cell lines." (PMID 26917489, 2016). "For instance, KDM5B and SNAI1 activities exhibited gradually increased in ER+ cells, aligning with their known roles in breast cancer metastasis." (PMID 40397381, 2025). "In MCF-7 breast cancer cells overexpressing KDM5B, also known as JARID1B, inhibition of KDME activity increased the sensitivity of breast cancer cells to IR and enhanced radiation-induced damage by blocking the catalytic function of KDM5 enzymes." (PMID 41369374, 2025). "GSKJ4 has a weak inhibitory ability on KDM5B, while KDM5B is also abnormally expressed in a variety of tumors, such as GBM and breast cancer." (PMID 37220590, 2023). "JARID1B/KDM5B is also known to be regulated by miR-138, miR-381-3p, and miR-486-5p as observed in breast cancer." (PMID 35087589, 2022). "KDM5B inhibition promoted the re-expression of tumor suppressor protein HEXIM1, and upregulated HEXIM1 aided in the inhibition of breast cancer cell proliferation using KDM5B inhibitors." (PMID 32751840, 2020). "Again, mRNA expression levels of PYGO2 and KDM5B were higher in Luminal, HER2+, and basal-like breast cancers, and ZMYND8 was higher in Luminal B and HER2+ subtypes compared with that in the normal-like subtype in the METABRIC dataset (p < 0.001)." (PMID 28055972, 2017). "Consistent with this, we found that the mRNA expression level of KDM5B was slightly higher in the HER2+ subtype, compared with luminal and basal-like subtypes, in both TCGA and METABRIC breast cancer samples." (PMID 28055972, 2017). "We found that three PHFs (PYGO2, KDM5B, and PHF20L1) were overexpressed at the mRNA level (Z-score > 1) in more than 40% of breast cancers." (PMID 28055972, 2017). "In this study, we identified four PHFs, PYGO2, KDM5B, PHF20L1, and ASH1L, which were most commonly amplified/overexpressed in breast cancer." (PMID 28055972, 2017). "Therefore, this study aimed to investigate the functional interplay between lysine demethylase 5B (KDM5B) and the Cullin-RING ligase 4B (CRL4B) complex in modulating cholesterol metabolism to promote ER+ breast cancer progression." (PMID 41654562, 2026). "Despite numerous KDM inhibitors being developed in various laboratories, no drugs specifically targeting KDM5B have been approved by the FDA for the management of breast cancer." (PMID 40764352, 2025). "We used an online database (ChIPBase v2.0) to predict the transcription factors for ZNF582-AS1, chr19:56, 393, 312-56, and 414, 800 (GRCh38/hg38), and the online tool suggested five potential candidates in breast cancer cell lines, namely CTCF, KDM5B, HIF1A, ARNT, and NRF1." (PMID 35681777, 2022). "In basal-like breast cancer, a significant increase in bromodomain-containing protein 4 (BRD4), lysine-specific demethylase 5B (KDM5B), and enhancer of zeste homolog 2 (EZH2) activities was detected in tumor cell populations after treatment with MEK and PI3K/mTOR inhibitors." (PMID 33597817, 2021). "Of note, KDM5B induces CTH and mediates therapeutic resistance in breast cancer." (PMID 33245716, 2020). "In determining that HMBA and 4a1 induce HEXIM1 expression by counteracting the inhibitory effects of KDM5B upon HEXIM1 expression, we may have perhaps determined how HEXIM1 expression is lost in breast cancer." (PMID 31805991, 2019).
breast carcinoma (continued). "A detailed analysis of expression levels of each PHF in the five breast cancer subtypes also revealed that expression levels of PYGO2 and KDM5B were higher in Luminal, HER2+, and basal-like, compared with their expression levels in the normal-like subtype of breast cancer." (PMID 28055972, 2017). "Compared with other breast cancer types, the highly metastatic MDA-MB-231 cells concurrently exhibited increased expression levels of Lysine-specific demethylase 5B protein (KDM5B) and long non-coding RNA (lncRNA), MALAT1, suggesting their functional association." (PMID 26917489, 2016). "While the KDM5B-NTT transcript is much less abundant than that one giving rise to the canonical PLU-1 isoform, the truncated protein is much more stable to proteasome degradation and can accumulate in breast cancer cells, although its relative amount is variable in different cell lines." (PMID 39000010, 2024). "Thymidine kinase-1 (TK1), lysyl oxidase (LOX), lysine demethylase 5B (KDM5B), proteasome 26S subunit non-ATPase 4 (PSMD4), and nuclear factor erythroid 2-like 3 (NFE2L3) genes are implicated in relapse and poor prognosis of patients with breast cancer." (PMID 37767092, 2023). "Several novel TFs with high enrichment scores such as KDM5B have not been widely studied in breast cancer, suggesting that they might be potential novel genes associated with breast cancer." (PMID 33045741, 2021). "The KDM5B--BF-1--PAX9 interaction may play a significant role in embryogenesis as well as in breast cancer, but the mechanism is not very clear and further evaluation is required in the future." (PMID 27974677, 2017). "To determine if KDM5B was sufficient for the activation of the increased TNBC oncoagression observed, we further evaluated the expression of KDM5B, c-Myc (a metastatic factor and mesenchymal marker) and other EMT markers in breast cancer tissues and cell lines." (PMID 26917489, 2016). "Further characterization of the consequences of PAH2 inhibition should also focus on whether this impacts function of the breast cancer oncoprotein EMSY, which has been shown to interact with PF1 and, more recently, KDM5B to repress expression of the anti-metastatic microRNA miR-31." (PMID 26460951, 2015). "Both miRNAs are down-regulated in several breast cancer cell lines compared with nontumorigenic human mammary epithelial cell line MCF10A, consistent with the higher expression levels of KDM5B and KDM5C in these cancer cells." (PMID 30080846, 2018). "In addition to its role in ER+ BCs, KDM5B contributes to BC progression in triple-negative breast cancer (TNBC), a highly aggressive subtype of breast cancer defined by a lack of ER, progesterone receptor, and human epidermal growth factor receptor 2 (HER2) expression." (PMID 36509829, 2022).